FLCN (folliculin)
Diseases named in the same sentence as FLCN in open-access papers (continued):
Sharing a sentence is not in itself a finding about the gene and the disease.
Fibrofolliculoma (33 papers, 2008 to 2025). Fibrofolliculoma is a clinically asymptomatic, 2-4 mm, skin-colored, dome-shaped smooth papule. "Major criteria include: (a) at least five skin lesions (trichodiscomas or fibrofolliculomas), with at least one confirmed histopathologically and appearing in adulthood or (b) a known pathogenic mutation in the FLCN gene." (PMID 40630489, 2025). "The European BHD diagnostic criteria suggest that a minimum of five fibrofolliculomas or trichodiscomas (with at least one confirmed histologically, occurring in adulthood) and the presence of a pathogenic FLCN germline mutation to be major criteria." (PMID 39300538, 2024). "The germline variant PRDM10Cys677Tyr curtails cellular folliculin expression and underlies a distinguishable syndrome characterized by extensive lipomatosis, fibrofolliculomas and renal cell carcinomas." (PMID 36440963, 2023). "BHD, aka folliculin gene-associated syndrome, is an autosomal dominant dermatological disorder characterized by fibrofolliculomas, trichodiscomas over the face, and diffusely distributed skin tags." (PMID 37435256, 2023). "Individuals with a germline mutation in the FLCN gene have a high lifetime risk for developing multiple and bilateral renal cell carcinomas of any histologic type, fibrofolliculomas of the skin, and lung cysts that can lead to spontaneous pneumothorax." (PMID 23874397, 2013). "The Birt-Hogg-Dube disease occurs as a result of germline mutations in the human Folliculin gene (FLCN), and is characterized by clinical features including fibrofolliculomas, lung cysts and multifocal renal neoplasia." (PMID 23874397, 2013). "B26 had a personal and family history of skin lesions (father and brother) as assessed by a dermatologist who reported features consistent with fibrofolliculoma, however, confirmatory skin biopsy was declined as was FLCN germline testing." (PMID 34604083, 2021). "The proband was initially diagnosed with BHD based on the presence of fibrofolliculomas, but no pathogenic germline variant was detected in FLCN, the gene associated with BHD." (PMID 36440963, 2023). "Meanwhile, four patients (16%) had fibrofolliculoma identified within 1 year of the FLCN gene test." (PMID 35666727, 2022). "Cases have been reported whereby patients with mutations of FLCN exhibit SP without the involvement of fibrofolliculomas or renal tumours." (PMID 20932317, 2010). "The folliculin (FLCN) gene, a tumor suppressor gene localized in the short arm of the chromosome (17p11.2), was first identified in 2001 and reported to be associated with PSP, fibrofolliculoma, pulmonary cyst, and Birt–Hogg–Dubé Syndrome‐associated kidney cysts." (PMID 31625278, 2019). "Importantly, loss of function mutations in the FLCN gene cause Birt–Hogg–Dube (BHD) syndrome, which is characterized by the formation of benign or malignant tumors in hair follicles (fibrofolliculomas), kidney, and lung, suggesting that FLCN is a tumor suppressor." (PMID 28686218, 2017). "In summary, FLCN alterations were initially recognized in patients with BHD syndrome, typically leading to oncocytic renal tumors, fibrofolliculomas, and lung cysts." (PMID 40277780, 2025).
kidney cancer (33 papers, 2011 to 2025). Primary or metastatic malignant neoplasm involving the kidney. "The development of kidney cancer in BHD patients typically involves loss of heterozygosity through gene silencing or inactivating somatic mutations of the wild-type FLCN allele." (PMID 39201746, 2024). "Birt–Hogg–Dubé syndrome (BHD) is a hereditary condition characterized by kidney cancer, primarily caused by mono-allelic germline loss-of-function mutations in the Folliculin (FLCN) gene, which is essential and conserved." (PMID 39201746, 2024). "Loss of heterozygosity, by gene silencing or an inactivating somatic mutation of the wild-type FLCN allele, is a prerequisite for kidney cancer development in BHD patients." (PMID 33459596, 2021). "Our integrated analysis reveals these genes and their protein products as candidate positive biomarkers for FLCN loss in BHD-related kidney cancer." (PMID 33459596, 2021). "Family screening for carriers of FLCN mutations is of outmost importance since kidney cancer is the most lethal potential complication of this syndrome." (PMID 30326848, 2018). "Studies suggest that the TERT mutation and germline mutations of FLCN are associated with both kidney cancer and PTC." (PMID 30046434, 2018). "For example, while most of the kidney cancer-related genes are subtype-specific, FLCN mutations lead to all subtypes of RCCs that have been observed in BHD syndrome patients and knockout mouse models." (PMID 26418749, 2015). "We used quantitative RT‐PCR to measure the levels of three TGF‐beta pathway components (TGFB2, INHBA, and SMAD3) and two TGF‐beta targets (THBS1 and CDKN2B) which were previously found to be significantly lower in FLCN‐deficient kidney cancer cells and tumors." (PMID 25121506, 2014). "A recent study has shown preferential toxicity of mithramycin and paclitaxel to FLCN-deficient kidney cancer cell line, UOK257." (PMID 24305604, 2013). "In this study, we chose paclitaxel for further study its effects on FLCN-deficient kidney cancer cells to find a more effective way to treat these cancer cells." (PMID 24305604, 2013). "A previous study has shown preferential toxicity of paclitaxel to FLCN-deficient kidney cancer cell line, UOK257." (PMID 24305604, 2013). "Preferential toxicity of paclitaxel to FLCN-deficient kidney cancer cells is associated with enhanced autophagy." (PMID 24305604, 2013). "According to the revised Chinese BHD criteria, 95 lung lesions (99%), 5 kidney cancers (6.4%), and 5 (5.8%) skin lesions met the clinical diagnostic criteria, 85 (98.8%) pathogenic FLCN mutations met the genetic diagnostic criteria, and 35 (35%) had first-degree relatives with confirmed diagnosis." (PMID 39300538, 2024). "Interestingly, TFE3 translocations and gene duplications (i.e., gain-of-function variants) are a relatively common cause of kidney cancer, associated with high mTORC1 activity, thus mimicking the effects of FLCN deletion in BHD syndrome." (PMID 35358174, 2022). "The identification of FLCN as the tumor suppressor associated with BHD syndrome led several research groups to investigate the mechanism by which the loss of functional FLCN results in kidney cancer." (PMID 32195250, 2020). "Mutations in the FLCN gene cause Birt-Hogg-Dube’ (BHD) syndrome, an inherited familiar cancer syndrome mainly characterized by skin and kidney cancer." (PMID 40189703, 2025). "LC3C has tumor-suppressing activity, and its expression is dependent on kidney cancer tumor suppressors, such as von Hippel–Lindau protein and folliculin." (PMID 37003503, 2023). "RhoA-GTP, an active form of RhoA, was increased by about 30% in kidney cancer cells with knockdown of FLCN, which co-localizes and interacts at the midbody during cytokinesis with p00717." (PMID 34031471, 2021). "Taken together however, the repository of FLCN target genes and proteins presented here provides a clear basis for further investigations into specific roles in kidney cancer and other BHD-related symptoms." (PMID 33459596, 2021).
kidney cancer (continued). "There are many reports on genes associated with kidney cancer pathogenesis, including VHL, FH, MET, FLCN, etc.." (PMID 32850947, 2020). "Taken together, these data are strongly supportive of a DENN domain‐dependent role for FLCN regulation of lysosome distribution through a Rab34/RILP axis in BHD kidney cancer cells." (PMID 27113757, 2016). "The findings suggest that genes associated with kidney cancer, including VHL, MET, FH, FLCN, TSC1, TSC2, and SDH, are involved in metabolic pathways linked to oxygen and iron or nutrient sensing, thus characterizing kidney cancer as a cellular metabolic disease." (PMID 35873461, 2022). "FLCN is a conserved, essential gene linked to diverse cellular processes but the mechanism by which FLCN prevents kidney cancer remains unknown." (PMID 33459596, 2021). "Despite potential selection and non-response bias in these two studies, malignant renal tumor was rarely detected in these Chinese FLCN mutation carriers, which strongly suggests a lower prevalence of renal malignancy in Chinses BHDS patients." (PMID 31615547, 2019). "However, the same family protein FLCN has been studied in breast cancer, kidney cancer and cervical cancer." (PMID 30524285, 2018). "On the other hand, predicted cell type compositions of BHD-associated kidney cancers were similar across all tumors, consistent with our previous notion that BHD-associated kidney cancer is genetically uniform with very few driver variants other than variants in the folliculin (FLCN) gene." (PMID 35874919, 2022). "Multiple genes linked with kidney cancer, including the VHL, MET, FLCN, fumarate hydratase, succinate dehydrogenase, TSC1, TSC2, and TFE3, were identified by genomic studies and have significantly altered the ways in which patients with kidney cancer are managed." (PMID 29254180, 2017). "Therefore the signaling consequences of FLCN deficient cells do not appear to align precisely with those of other tumors, or of other genetic diseases associated with kidney cancer and skin tumors, such as tuberous sclerosis complex." (PMID 23139756, 2012). "Genomic studies identifying the genes for kidney cancer, including the VHL, PBRM1, MET, FLCN, fumarate hydratase, succinate dehydrogenase, TSC1, TSC2, and TFE3 genes are known to play role in renal cell carcinoma development." (PMID 35709632, 2022). "Recently, several characteristic kidney cancer-related genes, including VHL, MET, FLCN, TSC1, TSC2, FH, and SDH, have been reported to affect the metabolic stress response." (PMID 33686951, 2021). "Previous studies have shown that seven known kidney cancer genes, VHL, MET, FLCN, TSC1, TSC2, FH, and SDH, are involved in pathways that respond to metabolic stress or nutrient stimulation, suggesting that kidney cancer is a disease of dysregulated cellular metabolism." (PMID 31649873, 2019). "Besides FLCN-deficient cell line UOK257, a cell line derived from a BHD patient’s kidney cancer, we also employed a RCC cell line, ACHN, with known FLCN expression and its FLCN expression could be effectively suppressed with siRNA." (PMID 24305604, 2013).
renal cell carcinoma (33 papers, 2010 to 2025). "Birt-Hogg-Dube disease is caused by mutations in the folliculin (FLCN) gene through which 30–45% of cases develop renal cell carcinoma (RCC)." (PMID 34447409, 2021). "Using Sanger sequencing we identify a heterozygous splice-site mutation in FLCN in lymphocyte DNA of a patient suffering from renal cell carcinoma." (PMID 28499369, 2017). "The human cell line UOK257, derived from the renal cell carcinoma of a patient with a germline mutation in the FLCN gene, harbors a truncated version of the FLCN protein." (PMID 23874397, 2013). "Recently, it has been demonstrated that paclitaxel exhibits preferential toxicity to folliculin (FLCN)-deficient renal cell carcinoma (RCC) line, UOK257, a cell line which originated from a patient with Birt–Hogg–Dube (BHD) syndrome." (PMID 24305604, 2013). "Mutations in the renal tumour suppressor protein, folliculin, lead to proliferative skin lesions, lung complications and renal cell carcinoma." (PMID 22977732, 2012). "Moreover, a recent investigation described four SMS patients exhibiting hallmark features of BHD, including renal cell carcinomas and/or cutaneous fibrofolliculomas, attributed to FLCN haploinsufficiency." (PMID 40724914, 2025). "In addition, the reintroduction of the wild type (WT) FLCN protein into the FLCN-deficient human renal cell carcinoma cell line UOK257 suppresses their growth as colonies in soft agar and restricts their growth as tumors when xenografted in SCID mice." (PMID 23874397, 2013). "Taken together, these findings reveal a novel paradigm in which loss of the FLCN-p0071 interaction and consequent defects in cell-cell adhesion, cell polarity and RhoA activity participates in the pathogenesis of renal cell carcinoma, skin tumors, and cystic airspace enlargement." (PMID 23139756, 2012). "Recent reports have described SMS patients with renal cell carcinomas and cutaneous fibrofolliculomas, hallmark features of BHD, linked to the deletion of FLCN in addition to RAI1." (PMID 40724914, 2025). "Genes implicated in renal cell carcinoma development—VHL, TSC1/2, and FLCN—will be used as examples to explore this concept, as well as how pathogenic mutations of tumor suppressors cause disease by disrupting protein chaperoning, maturation, and function." (PMID 39352796, 2024). "Because the principal role of folliculin is tumor suppression, BHD is associated with cancer, including renal cell cancer and perhaps even lung cancer." (PMID 28151982, 2017). "FLCN mutation carriers have been reported to have an increased lifetime risk of developing renal cell carcinoma (RCC), they should be advised to take some preventive measures, largely aimed at early recognition and treatment of RCC." (PMID 27229674, 2016). "His findings provide a recommendation for all BHD patients to have renal cell carcinoma screening regardless of the underlying FLCN variant." (PMID 35070081, 2022). "Heterozygous loss-of-function germline mutations in FLCN cause Birt–Hogg–Dubé (BHD) syndrome, which is marked by chronic development of lung cysts, abundant benign dermal hamartoma-like tumors, and a high incidence of renal cell carcinoma (RCC)." (PMID 35358174, 2022). "Risk factors and comorbidities might be associated to renal cell carcinoma, while a small fraction of 2–3% emerges from patients with predisposing cancer syndromes, typically associated to hereditary mutations in VHL, folliculin, fumarate hydratase or MET genes." (PMID 38512353, 2024). "Targeting several cell surface RTKs simultaneously, in addition to EGFR, or inactivating intracellular kinases that function as converging hubs of deregulated signalling pathways may be an effective therapeutic strategy for treating FLCN-dependent renal cell cancers." (PMID 28656962, 2017). "A decameric peptide derived from FLCN was sufficient to bind and inhibit LDHA in renal cell carcinomas, leading to cell death." (PMID 35070081, 2022).
renal cell carcinoma (continued). "The loss of FLCN is linked with an activity of the AKT/mTORC pathway, leading to Birt–Hogg–Dubé autosomal dominant syndrome and increasing the risk of hybrid oncocytic renal cell carcinoma (RCC) and pulmonary cysts." (PMID 32850947, 2020). "We synchronized isogenic derivatives of the human renal cell carcinoma cell line UOK257 that express either WT FLCN, mutant FLCN, or the vector (control) and we studied their progression through the cell cycle." (PMID 23874397, 2013). "In order to investigate the cellular functions of FLCN, we used the human cell line UOK257, which was generated from the renal cell carcinoma of a BHD patient and expresses a truncated, putatively null form of the FLCN protein." (PMID 23874397, 2013). "This is not an in vitro-only phenomenon; renal cell carcinomas growing in FLCN KO mouse kidneys display strong activation of the EGFR signalling pathway and treatment of FTC-133 FLCN−/− mouse xenografts with the EGFR inhibitor Afatinib slowed tumour growth." (PMID 28656962, 2017).
Renal cyst (16 papers, 2013 to 2026). A fluid filled sac in the kidney. "Animal studies have shown that the FLCN gene mutations can spontaneously lead to renal cysts, adenomas, and carcinomas." (PMID 40630489, 2025). "A number of tumor suppressor genes that have established roles in renal tumorigenesis, namely VHL, TSC1, TSC2 and FLCN, also predispose to renal cyst formation, a common hallmark of ciliopathy syndromes." (PMID 23369289, 2013). "Using several models of renal cystic disease, including those associated with loss of folliculin and polycystin-1 (PKD1) activities, it was observed that nuclear TFEB translocation and functional responses associated with TFEB activation characterize cyst-lining epithelia." (PMID 36794754, 2023). "Similar to renal cysts developed from our Flcnflox/flox/Ksp-Cre mice, these allograft tumors also exhibited the activation of the mTOR pathway, which is consistent with the previous findings in FLCN-deficient cell lines and animal models." (PMID 26418749, 2015). "FLCN forms a complex with folliculin-interacting proteins 1 and 2 (FNIP1 and FNIP2), and kidney-specific double homozygous inactivation of FNIP1/2 or FLCN in mice results in enlarged multi-cystic kidneys." (PMID 39352796, 2024). "Nineteen BHDS patients with pathogenic FLCN mutations, showed lung phenotype with skin fibrofolliculomas in 4 patients and RCC/renal cysts in 2 patients, respectively." (PMID 35477461, 2022). "The knockdown of FLCN in salivary glands and cystic kidneys triggered metabolic reprogramming pathways by modulating PGC1α and TFE3 transcription and the AMPK-mTOR pathway to support cell proliferation." (PMID 35328408, 2022). "In mice, homozygous kidney-specific FLCN knockouts display enlarged polycystic kidneys, and heterozygous whole-body FLCN knockout mice develop renal cyst and malignancies that are reminiscent of human BHD tumors." (PMID 28039480, 2017). "All of the FLCN KO (Flcnflox/flox/Sglt2-Cre) mice over 6 months of age develop cystic kidneys and more than 50% of the mice also develop renal tumours." (PMID 28656962, 2017). "However, loss of functional folliculin in these settings is not typically characterized by renal cystic disease but rather by tumors such as oncocytomas." (PMID 36794754, 2023).
cyst (11 papers, 2008 to 2025). A sac-like closed membranous structure that may be empty or contain fluid or amorphous material. "Our findings indicate that reliable chest CT features suggesting the need to screen for FLCN gene mutations include variations in cyst size and the presence of cysts >2.1 cm in diameter, predominantly occurring in the bilateral basal lung zones." (PMID 36673012, 2023). "Areas under the receiver operating characteristic curves for predicting FLCN gene mutations were 0.955 and 0.909 for maximal cyst diameter and diversity in size, respectively." (PMID 36673012, 2023). "Furthermore, maximal cyst diameter exhibited the highest AUC for predicting FLCN gene mutation in the ROC analysis." (PMID 36673012, 2023). "Additionally, in the ROC curve analysis for predicting FLCN gene mutations, the maximal cyst diameter had the highest AUC value, with an optimal cut-off value of 2.1 cm." (PMID 36673012, 2023). "Similarly, in the multivariate analysis, only the maximal cyst diameter was significantly correlated with the presence of FLCN gene mutations (OR [95% CI], 6.884 [1.745–117.748])." (PMID 36673012, 2023). "FLCN protein (folliculin) has a tumour suppressor activity interfering with the mTOR signalling pathway, a fact that provides a plausible explanation for cyst formation." (PMID 35176117, 2022). "Downregulation of FLCN or p0071 led to irregularly shaped and less organized cyst formation with decreased lumen size." (PMID 23139756, 2012). "Cyst initiation in both the kidney and lung may initiate during development due to altered epithelial integrity together with the fundamental role of FLCN in embryonic stem cell differentiation." (PMID 25121506, 2014). "Parallels have been discussed to the cyst formation in LAM that might result from interactions between the estrogen signaling pathway and the mechanistic target of rapamycin (mTOR), in which both the tuberous sclerosis complex and FLCN are involved." (PMID 38020174, 2023).